RNU6-1133P (RNA, U6 small nuclear 1133, pseudogene)
Synonyms: formerly RNU6-186P
Gene: Small nuclear RNA gene on chromosome 6 (31,083,010 to 31,083,109, forward strand). Ensembl gene ENSG00000222895.
Homologues: Orthologues: chimpanzee U6 (100% identical), macaque U6 (82% identical), mouse Gm55087 (48% identical). Paralogues in human: RNU6-204P (80% identical), RNU6-1309P (79% identical), RNU6-1209P (78% identical), RNU6-735P (78% identical), RNU6-1099P (77% identical), RNU6-11P (77% identical), RNU6-302P (77% identical), RNU6-37P (77% identical), RNU6-560P (77% identical), RNU6-744P (77% identical), RNU6-797P (77% identical), RNU6-1048P (76% identical), and 1285 more.